FBXW11 (F-box and WD repeat domain containing 11)
Diseases named in the same sentence as FBXW11 in open-access papers (continued):
Sharing a sentence is not in itself a finding about the gene and the disease.
leiomyoma (1 paper, 2023). A well-circumscribed benign smooth muscle neoplasm characterized by the presence of spindle cells with cigar-shaped nuclei, interlacing fascicles, and a whorled pattern. "Others have also reported overexpression of WIF1 and other WNT-protein inhibitors such as SFRP1, FBXW11, NKD1, and SFPR4 in leiomyomas." (PMID 36835153, 2023).
liver cancer (1 paper, 2016). An epithelial or non-epithelial malignant neoplasm that arises from the liver. "In four cancers, mutations at the N-terminal disordered region of the protein are predicted to perturb interactions with BTRC, FBXW11 and HLA-A, whereas only two of these cancers (liver cancers) have additional mutations at the armadillo region perturbing interactions with other proteins." (PMID 27698488, 2016).
lung adenocarcinoma (1 paper, 2023). A carcinoma that arises from the lung and is characterized by the presence of malignant glandular epithelial cells. "In contrast, IHC staining of FBXW11 showed that FBXW11 was expressed in the urinary bladder, breast, and lung, but was not expressed in BLCA, BRCA, and lung adenocarcinoma (LUAD)." (PMID 36982338, 2023).
serous ovarian cancer (1 paper, 2025). "FBXW11 was abnormally expressed at low levels in high-grade serous ovarian cancer (HGSOC) tissues, and low levels of FBXW11 were associated with shorter overall survival (OS) and progression-free survival (PFS) in HGSOC patients." (PMID 40747341, 2025). "However, FBXW11 expression in high-grade serous ovarian cancer (HGSOC) and its relationship with PARPi sensitivity have not been investigated." (PMID 40747341, 2025).
cancer (15 papers, 2015 to 2025). A tumor composed of atypical neoplastic, often pleomorphic cells that invade other tissues. "Owing to alterations in the microenvironment and specific target substrates in different types of cancer, FBXW11 exerts dual effects, both promoting and inhibiting cancer progression." (PMID 40747341, 2025). "Accumulating evidence suggests that FBXW11 has differential expression patterns across various tumor types and plays a variety of roles in human cancer by targeting different substrates." (PMID 40747341, 2025). "Of all FBXW members, FBXW9 was the most frequently upregulated across 17 cancer types (14/17), while FBXW11 was the most frequently downregulated gene in cancers (10/17)." (PMID 36982338, 2023). "FBXW11 is a ubiquitin–proteasome system (UPS) that plays a key role in regulating various signaling pathways by post-translational modifications regulating cancer cell tumorigenesis." (PMID 36476410, 2022). "FBXW11 plays a pivotal role in cancer development by governing the turnover of key proteins associated with tumor cell proliferation and mobility." (PMID 34642302, 2021). "Other FBXW proteins, β-TrCP1 (also named FBXW1) and β-TrCP2 (also named FBXW11), exhibit their oncogenic or tumor-suppressive functions based on the specific cancer type or cellular context." (PMID 30999935, 2019). "FBXL7 and FBXW11 are also involved in UCHL1 (ubiquitin carboxyl-terminal esterase L1)-mediated stem-like cancer cell function in high-grade glioma." (PMID 30999935, 2019). "Interestingly, the current pan-cancer analysis also provided novel findings uncovering the upregulation of FBXW9 in the majority of cancer types examined, as well as the downregulation of FBXW11 in multiple cancer types." (PMID 36982338, 2023). "To date, no study has reported the effect of the interaction of CUL7 and Fbxw11 in cancer." (PMID 33130829, 2020). "Therefore, dysregulation of Fbxw8 or Fbxw11 might be an effective therapeutic approach for CUL7-related cancers." (PMID 33130829, 2020). "In contrast, downregulation of FBXW11 was observed in BLCA, BRCA, kidney chromophobe (KICH), and 7 other cancer types." (PMID 36982338, 2023). "Although FBXW11 has been investigated in embryogenesis and cancer, its expression has not been evaluated in osteogenic cells." (PMID 37199076, 2023). "In addition, by qPCR and RNA-seq we identified several cancer-related genes that regulated by AS of APEX1, which included AXIN1, GCNT2, SMAD3, CTBP2, PPARD, and FBXW11." (PMID 35780128, 2022). "If these two proteins interact, we hypothesize that the Fbxw11-mediated regulation of the cell cycle and the NF-κB signaling pathway might be related to the interaction of Fbxw11 with CUL7 in these cancers." (PMID 33130829, 2020). "However, the role of CUL7 in these types of cancers is not clear, and whether CUL7 interacts with Fbxw11 in these cancers needs to be further explored." (PMID 33130829, 2020).
tumor (12 papers, 2014 to 2025). "F-box and WD repeat domain containing 11 (FBXW11) is a member of the F-box protein family that regulates the ubiquitination of key factors associated with tumor growth and aggressiveness." (PMID 34642302, 2021). "Taken together, our findings strongly suggest that for 30/32 BCA cases (93.7%), activation of the Wnt/β-catenin signalling pathway, either through mutation of CTNNB1 at p.I35T or FBXW11 at p.F517S is the primary mechanism of tumourigenesis in this tumour entity." (PMID 40389436, 2025). "Tumor growth was significantly increased in groups expressing high levels of Fbxw11 variants." (PMID 29555946, 2018). "Conversely, in non-small cell lung cancer, FBXW11 is downregulated as an immediate target of miR-182, similarly promoting tumor proliferation and invasion." (PMID 40747341, 2025). "FBXW11 performs distinct functions in various tumor types, acting as either an oncogene or tumor suppressor." (PMID 40747341, 2025). "The upregulation of FBXW11, an immediate target of miR-182, in cervical cancer enhances tumor proliferation." (PMID 40747341, 2025). "FBXW11 overexpression accelerated the degradation of the HIC1 protein in tumor cells, whereas the knockdown of FBXW11 decelerated this process compared to cells with normal FBXW11 expression." (PMID 34642302, 2021). "In summary, FBXW11 plays an indispensable role in promoting tumor growth, maintaining stem-cell-like features in tumor cells and inducing liver metastasis in CRC." (PMID 34642302, 2021). "In both CRC cell lines, FBXW11 overexpression effectively enhanced cell migration and invasion, whereas the downregulation of FBXW11 significantly impaired the motility of tumor cells." (PMID 34642302, 2021). "FBXW11 was regulated by miR-106b-25 cluster and involved in tumor invasion and metastasis." (PMID 25115392, 2014). "The present work, therefore, contributes to the understanding of FBXW11 role in osteogenic cells by evaluating its modulation both during osteogenic commitment and in altered osteoblastic cells characterized by RUNX2 mutations or resulting from tumour transformation." (PMID 37199076, 2023). "MS analysis identified F-box and WD repeat domain containing 11 (FBXW11), which is an important component of the SCF (SKP1-CUL1-F-box) E3 ubiquitin ligase complex and is involved in the progression of several tumours." (PMID 39856764, 2025). "Reduced expression of FBXW11 was reported in NSCLC tissues, and this protein was recognized as a tumor suppressor." (PMID 33142748, 2020). "Specifically, circMAN1A2 competes with F-Box and WD repeat domain containing 11 (FBXW11) to bind and stabilize splicing factor proline and glutamine rich (SFPQ) expression, inhibiting T cell receptor stimulation and reducing T cell anti-tumor activity." (PMID 40771798, 2025). "Although FBXW11 has been studied in haematopoietic stem cells and in various types of tumours, no studies have ever been performed to evaluate the role of FBXW11 in the osteogenic lineage." (PMID 37199076, 2023).
infection (1 paper, 2016). The state of being infected such as from the introduction of a foreign agent such as serum, vaccine, antigenic substance or organism. "Next we examined the effects of knocking down SKP1, CUL1, FBXW11 alone or in combination, in the presence or absence of PKR, on infection levels of RVFV ZH501 in HeLa cells." (PMID 26837067, 2016).
FBXW11 also shares sentences with these, for which no sentence is quoted: acute lymphocytic leukemia (1 paper); acute myeloid leukemia (1); B-cell acute lymphocytic leukemia (1); chondrosarcoma (1); chronic lymphocytic leukemia (1); cleidocranial dysplasia (1); developmental delay (1); esophageal carcinoma (1); genetic disorders (1); Intellectual disability (1); neurodevelopmental disorder (1); non-small cell lung carcinoma (1); prostate carcinoma (1); uterine tumors (1); viral infection (1).